PARD6A (par-6 family cell polarity regulator alpha)
Description:
Adapter protein involved in asymmetrical cell division and cell polarization processes. Probably involved in the formation of epithelial tight junctions. Association with PARD3 may prevent the interaction of PARD3 with F11R/JAM1, thereby preventing tight junction assembly. The PARD6-PARD3 complex links GTP-bound Rho small GTPases to atypical protein kinase C proteins. Regulates centrosome organization and function. Essential for the centrosomal recruitment of key proteins that control centrosomal microtubule organization.
Synonyms: PAR-6; PAR-6A; TIP-40; TAX40; PAR6alpha; PAR6; PAR6C
Tractability: Antibody: its Gene Ontology location is reachable by antibodies, with high confidence; UniProt places it where antibodies can reach, with medium confidence. PROTAC: UniProt records ubiquitination sites on it; ubiquitination databases record sites on it.
Gene: Protein-coding gene on chromosome 16 (67,660,909 to 67,662,777, forward strand). Ensembl gene ENSG00000102981.
Subcellular location: Cytoplasm; Cell membrane; Cell projection, ruffle; Cell junction, tight junction; Cytoplasm, cytoskeleton, microtubule organizing center, centrosome, centriolar satellite; Cytoplasm, cytoskeleton, microtubule organizing center, centrosome
Subcellular location (Human Protein Atlas): Actin filaments; Cell Junctions; Cytosol; Plasma membrane
Pathways (Reactome):
Signal Transduction: Asymmetric localization of PCP proteins; CDC42 GTPase cycle; RAC1 GTPase cycle; RHOU GTPase cycle; RHOV GTPase cycle; TGF-beta receptor signaling in EMT (epithelial to mesenchymal transition)
Cell-Cell communication: Tight junction interactions
Gene Ontology:
Molecular function: protein binding; protein-macromolecule adaptor activity; GTP-dependent protein binding; small GTPase binding
Biological process: centrosome cycle; establishment or maintenance of epithelial cell apical/basal polarity; positive regulation of protein localization to centrosome; cell-cell junction maintenance; establishment or maintenance of cell polarity; regulation of cellular localization; viral process
Cellular component: cell junction; centriolar satellite; centrosome; cytosol; PAR polarity complex; plasma membrane; apical plasma membrane; bicellular tight junction; cell cortex; nucleus; tight junction; cytoplasm; ruffle
Genetic constraint (gnomAD): Loss-of-function variants: 20 observed, 19.06 expected, observed/expected ratio (o/e) 1.05, 90% interval 0.74 to 1.52. The upper end of that interval is the gene's LOEUF score, 1.52, which puts it in group 6 of 6, group 1 being the genes least tolerant of losing a copy. Missense variants: 411 observed, 482.69 expected, observed/expected ratio (o/e) 0.85, 90% interval 0.79 to 0.92. Synonymous variants: 214 observed, 205.98 expected, observed/expected ratio (o/e) 1.04, 90% interval 0.93 to 1.16.
Homologues: Orthologues: chimpanzee PARD6A (99% identical), macaque PARD6A (99% identical), dog PARD6A (96% identical), pig PARD6A (95% identical), guinea pig PARD6A (95% identical), rabbit PARD6A (93% identical), mouse Pard6a (93% identical), rat Pard6a (87% identical), zebrafish pard6a (57% identical), Drosophila melanogaster par-6 (45% identical), Caenorhabditis elegans par-6 (40% identical). Paralogues in human: PARD6G (52% identical), PARD6B (52% identical).
Diseases named in the same sentence as PARD6A in open-access papers:
PARD6A is named in the same sentence as 31 diseases in open-access papers, as found by Europe PMC text mining. Sharing a sentence is not in itself a finding about the gene and the disease. The quoted sentences say what the papers report.
Insulin resistance (1 paper, 2019). Increased resistance towards insulin, that is, diminished effectiveness of insulin in reducing blood glucose levels. "Rho family GTPase 3 (RND3), PARD6A, TLE2, FBLN2, COL4A1, and COL4A2 are novel biomarkers for the development of insulin resistance." (PMID 30678306, 2019).
metastatic carcinoma (1 paper, 2021). A carcinoma which has spread from the original site of growth to another anatomic site. "Of note, PRICKLE1 interacted with PARD6A, a cell membrane protein which plays a role in cell polarization and the epithelial-to-mesenchymal transition (EMT) that represents the invasive phenotype in metastatic carcinomas." (PMID 34001134, 2021).
mucinous ovarian tumors (1 paper, 2022). "In the present study, the protein levels of PARD6A was found up-regulated in ovarian cancer tissues, especially in serous and mucinous ovarian tumors, and then the expression levels of PARD6A in a variety of ovarian cancer cell lines were compared." (PMID 35379775, 2022).
osteoporosis (1 paper, 2024). A condition of reduced bone mass, with decreased cortical thickness and a decrease in the number and size of the trabeculae of cancellous bone (but normal chemical composition), resulting in increased fracture incidence. "Interestingly, the expression of PARD6A and p-SMAD2, two genes enriched in the TGF-beta receptor signaling pathway, were significantly decreased in DEX-induced osteoporosis cells compared with that in control cells." (PMID 38454404, 2024).
ovarian carcinoma (1 paper, 2022). A malignant neoplasm originating from the surface ovarian epithelium. "In the current study, starting from the cellular functions of PARD6A, we studied the roles of PARD6A in EMT of ovarian cancer cells and the underlying mechanisms regulating these functions." (PMID 35379775, 2022). "Instead, our in vitro and in vivo results clearly showed that the expression of PARD6A was positively correlated with the migration and invasion characteristics of ovarian cancer cells." (PMID 35379775, 2022). "More importantly, there haven’t been any studies focusing on the effects of PARD6A on EMT in ovarian cancer which is particularly prone to migrate and invade." (PMID 35379775, 2022). "To further investigate the molecular mechanisms how PARD6A expression affects migration and invasion of ovarian cancer cells, we were interested in searching for signaling pathways involved in these processes." (PMID 35379775, 2022). "PARD6A knockdown suppressed EMT of SKOV3 and A2780 cells in vitro and ovarian cancer metastasis in vivo, while overexpression of PARD6A promoted EMT in HO8910 and OVCAR8 cells." (PMID 35379775, 2022). "In this study, we identified a novel role of PARD6A as an inducer of cell migration and invasion, which is likely to play an important role in metastasis of ovarian cancer." (PMID 35379775, 2022). "In summary, our results indicated that PARD6A affected EMT of ovarian cancer cells through SNAIL1 signaling pathways, which subsequently modulated the expression of VIMENTIN and E-cadherin." (PMID 35379775, 2022). "It was indicated that PARD6A affected EMT of ovarian cancer cells through SNAIL1 signaling pathway and subsequently modulated the expression of VIMENTIN and E-cadherin, which was further confirmed by knockdown and overexpression of SNAIL1 experiments." (PMID 35379775, 2022). "All these results indicate that PARD6A clinically correlates well with metastases of ovarian cancer." (PMID 35379775, 2022). "By manipulating the expression of PARD6A in cells, we studied the biological functions of PARD6A in ovarian cancer cells." (PMID 35379775, 2022). "Consistent with results of in vitro experiments, PARD6A knockdown significantly suppressed metastases of ovarian cancer cells in vivo." (PMID 35379775, 2022). "Together with earlier results, it was indicated that PARD6A promotes migration and invasion of ovarian cancer cells." (PMID 35379775, 2022). "The molecular pathways of EMT in ovarian cancer cells mediated by PARD6A-Integrin β1-ILK-SNAIL1 and finally implemented by E-cadherin and VIMENTIN also provide a novel strategy for drug development in the future." (PMID 35379775, 2022). "In addition, it was confirmed that PARD6A regulated the migration and invasion of ovarian cancer cells through regulating important molecules in EMT pathways such as SNAIL1, E-cadherin, and VIMENTIN." (PMID 35379775, 2022). "We found that PARD6A was significantly highly expressed in tissues of ovarian cancer patients in III-IV stages, poorly differentiated or with lymphatic metastases versus I-II stages, moderately or well differentiated, or without lymphatic metastases, respectively." (PMID 35379775, 2022). "When mRNA levels of SNAIL1, E-cadherin, and VIMENTIN were demonstrated to be affected by PARD6A expression, it was indicated that PARD6A likely affects EMT of these ovarian cancer cells through regulating SNAIL1 signaling pathway, thus acting on the downstream E-cadherin and VIMENTIN." (PMID 35379775, 2022). "In sum, knockdown of PARD6A gene suppressed EMT of ovarian cancer cells in vitro and in vivo." (PMID 35379775, 2022). "Functional experiments were carried out to study the roles of PARD6A in EMT of ovarian cancer in vitro and in vivo, and EMT pathways potentially affected by PARD6A expression were screened." (PMID 35379775, 2022).
ovarian carcinoma (continued). "The molecular pathways of EMT mediated by PARD6A-Integrin β1-ILK-SNAIL1 and finally implemented by E-cadherin and VIMENTIN may provide a novel strategy for drug development for ovarian cancer therapy in the near future." (PMID 35379775, 2022). "The protein levels of RhoA did not change significantly in any of four types of ovarian cancer cells no matter in which PARD6A was overexpressed or silenced." (PMID 35379775, 2022).
cancer (16 papers, 2012 to 2025). A tumor composed of atypical neoplastic, often pleomorphic cells that invade other tissues. "PARD6A is a cell membrane protein that plays a pivotal role in enhancing the migration, invasion, and proliferation of cancer cells." (PMID 33995018, 2021). "So far, the roles of PARD6A in EMT of cancers originating from epithelial cells are unclear." (PMID 35379775, 2022).
PARD6A also shares sentences with these, for which no sentence is quoted: tumor (14 papers); breast carcinoma (10); prostate carcinoma (7); cyst (5); lung carcinoma (5); non-small cell lung carcinoma (5); pancreatic cancer (2); clear cell ovarian cancers (1); cocaine dependence (1); colorectal adenocarcinoma (1); gastric cancer (1); gastrointestinal stromal tumor (1); glioblastoma (1); glioma (1); Hyperglycemia (1); intestinal obstruction (1); melanoma (1); nicotine dependence (1); opioid dependence (1); Renal cyst (1); rheumatoid arthritis (1); schizophrenia (1); soft tissue sarcoma (1); squamous carcinoma (1); staphylococcus aureus infection (1).